PDPN (podoplanin)
Diseases named in the same sentence as PDPN in open-access papers (continued):
Sharing a sentence is not in itself a finding about the gene and the disease.
tumor (continued). "Taken together, findings from the current study and previous studies suggest that podoplanin-positive CAFs may promote tumor progression, thereby decreasing survival." (PMID 36376711, 2023). "Therefore, our results indicate that circITGB6 promotes tumor metastasis though enhancing PDPN mRNA stability." (PMID 37898647, 2023). "The anti-mouse PDPN mAbs could be useful in revealing the importance of PDPN-positive lymphocytes in cancer immunity and obtaining proof-of-concept for tumor therapy." (PMID 37894446, 2023). "We highlight that PDPN overexpression is an independent prognostic indicator, and promotes macrophage M2 polarization and neutrophil degranulation, ultimately devotes to the formation of an immunosuppressive tumor microenvironment." (PMID 36434176, 2023). "The upregulation of PDPN in tumor cells was additionally confirmed by immunofluorescence staining." (PMID 37095087, 2023). "Therefore, it was concluded that PDPN can have a role in the tumor cell differentiation and neoplastic progression of OSCC." (PMID 37273383, 2023). "Podoplanin (PDPN), also known as D2-40, gp36, T1α, aggrus, and OTS-8, is a transmembrane receptor glycoprotein that is involved in several contexts of cell migration, including tumor cells, wound healing, and cancer associated fibroblasts." (PMID 37298679, 2023). "These include CTHRC1, INHBA, BGN, and PDPN, all of which are known to promote tumor progression." (PMID 38036590, 2023). "In a tumor environment, other cells could also be sources of podoplanin inducing platelet activation, such as vascular endothelial cells (VECs) and macrophages near the leaky vessels." (PMID 37770941, 2023). "In addition, other CAFs markers (vimentin and podoplanin) were also introduced to verify the status of CAFs in tumor of xenograft models." (PMID 36727832, 2023). "Additionally, CDH1 expression (epithelial marker) was observed in basal SCC25-derived tumours whereas mesenchymal SCC15 tumours were positive for PDPN (p-EMT marker)." (PMID 36949044, 2023). "Podoplanin is specifically expressed in lymphatic cells, and vWF is a marker of vascular endothelial cells; these are useful markers for differentiating lymphatic and blood vessels in tumor tissues." (PMID 37175975, 2023). "Pancreatic stellate co-cultured with PDACs could differentiate both POSTN-positive CAFs (least protumoral) to myosin heavy chain 11 (MYH11) and PDPN-expressed (tumor-supportive) CAFs." (PMID 38234683, 2023). "In addition, other CAFs markers (vimentin and podoplanin) were also introduced to verify the status of CAFs in tumor of KPC mice." (PMID 36727832, 2023). "Furthermore, administration of humLpMab-23-f in tumor-bearing mice completely suppressed the growth of CHO/PDPN xenografts and exerted potent antitumor effects in PC-10 and LN319 xenografts." (PMID 37894446, 2023). "Thus, with increasing in grades of OSCC, the location of PDPN within the tumor islands showed statistically significant results (p=0.003)." (PMID 37273383, 2023). "In particular, DKK3 and PDPN were both increased markedly on tumor-proximal cells." (PMID 37350578, 2023). "Furthermore, the sialylated podoplanin (PDPN) on CAFs plays a key role in tumor-cell-induced platelet aggregation; however, the deprivation of sialic acid reduces this function within the TME." (PMID 37894470, 2023). "The upregulation of PDPN correlates with malignant progression in several tumor types." (PMID 36671802, 2023). "In those tumors, PDPN was almost exclusively expressed in tumor-associated macrophages, but not in other tumor-infiltrating leukocytes." (PMID 37898403, 2023). "In addition, immunofluorescence staining of tumor histology samples from CRC patients revealed colocalization of PDPN, whose gene is part of the IL1R1+ iCAF set, and IL1R1 in the stromal tissue (lower-right panel for quantification)." (PMID 37460545, 2023). "Overexpression of podoplanin in both tumor cells and stroma of cSCC have been reported." (PMID 36793738, 2023).
tumor (continued). "PDPN-expressing CAFs are tumor-promoting by constructing immunosuppressive TME, which may be modulated by TGF-β production and CD204+ tumor-associated microphages infiltration." (PMID 36937386, 2023). "We observed that ADAM12+ MSCs (expressing GFP) localized specifically at the tumor margin, a transition zone enriched in stromal cells expressing various levels of PDPN and smooth muscle actin alpha 2 (αSMA+), collagenous ECM, T cells, CD206+ TAMs and blood vessels." (PMID 37798557, 2023). "Thus, the PDPN expression at the periphery of tumor nests signifies its high proliferative capacity, and central cells suggest terminal differentiation of tumor cells." (PMID 37273383, 2023). "Podoplanin is involved in tumor cell actin reorganization and may increase invasion by enhancing cell motility." (PMID 36505148, 2022). "The downregulation of E-cadherin in podoplanin (+) keratinocytes may contribute toward the dermal penetration of tumor cells by decreasing cell adhesion between basal cells to create gaps for invasion." (PMID 35163233, 2022). "It has been proposed that the expression of podoplanin focally in the peripheral layer of the tumor nest may indicate reduced biological aggressiveness than the diffuse pattern of podoplanin expression." (PMID 36247509, 2022). "However, under pathological conditions podoplanin expression is upregulated in various cells, such as keratinocytes, fibroblasts, tumor cells, and inflammatory cells, and plays pivotal roles in different diseases." (PMID 35163233, 2022). "Interestingly, previous studies and STRING analysis indicate that PDPN expression was coordinated with the expression of other tumor promoters, specifically Kdr/Vegfr2 and Wt1, that were induced by oncogenic Src kinase activity." (PMID 35177067, 2022). "Previously, we reported that podoplanin expression in peritumoral basal keratinocytes, but not in tumor cells, is associated with tumor thickness and dermal invasion." (PMID 35163233, 2022). "Nonetheless, macrophage amplification in LNs—for instance, via an induction of podoplanin expression in LECs or via blockade of CD200 or BST2—could help to activate endogenous as well as vaccine-induced tumor immunity." (PMID 35892863, 2022). "After 21 days of implantation, most (around 84%) of the PDPN+ fibroblasts in tumours were YFP+." (PMID 36171287, 2022). "PDPN has also been reported to be expressed in cells with tumor-initiating potential." (PMID 35159384, 2022). "The role of podoplanin in tumor invasion and metastasis raises the possibility that it could be used as a predictive marker for lymph node metastasis in HNSCC." (PMID 36247509, 2022). "In addition, PDPN was found to interact functionally with the tumor promoters Kdr/Vegfr2 and Wt1 which were induced by Src, but not affected by contact normalization." (PMID 35177067, 2022). "In some cancers, such as pancreatic adenocarcinoma, the tumor-derived MVs express procoagulant molecules such as tissue factor (TF) and podoplanin and adhesion molecules such as P-selectin, allowing them to interact with platelets and other cell types to promote tumor growth and metastasis." (PMID 35159000, 2022). "Increased expression of podoplanin in invasive front of tumor and its consistent role in tumor progression suggest that podoplanin might have a role as a biomarker in predicting lymph node metastasis." (PMID 36247509, 2022). "In lung tumor cases, PDPN-positive CAFs promote tumor cell malignancy." (PMID 35159384, 2022). "Podoplanin expression increased with the grade of the tumor." (PMID 36247509, 2022). "Experimental studies suggest that podoplanin may be targeted both on its intracellular and extracellular domains to alter the motility of tumor cells." (PMID 36247509, 2022). "Furthermore, EMPD cells are positive for TGF-β expression, suggesting that tumor cells control peritumoral keratinocytes to assist tumor invasion by upregulating podoplanin via TGF-β." (PMID 35163233, 2022).
tumor (continued). "Podoplanin on tumor cells is the only known endogenous ligand of CLEC-2, a platelet receptor." (PMID 35936717, 2022). "As podoplanin expression was required for optimal macrophage adhesion to LN LECs in vitro, we sought to confirm this hitherto unknown function of podoplanin in tumor-draining LNs in vivo." (PMID 35892863, 2022). "We have previously reported the construction and efficacy of NZ-1-CAR-T cells that target PDPN;12 however, NZ-1 CAR-T cells may have an on-target-off-tumor effect because they may recognize low levels of PDPN even in normal tissues." (PMID 35991754, 2022). "To understand if induction of PDPN knockdown after intracranial injection could slow tumor growth in vivo, we fed animals doxycycline after implantation and for the duration of the study (n=5 mice per condition)." (PMID 36059614, 2022). "Thus, over the past few decades, podoplanin has been used to understand tumor behavior and progression in various carcinomas." (PMID 36247509, 2022). "Podoplanin affects tumor invasion, progression, and lymphatic vessel development." (PMID 36505148, 2022). "Although blocking podoplanin inhibits tumor cell metastasis, platelet-targeting CLEC-2 inhibitors might be preferred as they reduce hematogenous metastasis rates without a significant increase in bleeding risk." (PMID 35936717, 2022). "Acquisition of PDPN expression at the tumor front may therefore drive invasion into surrounding tissue during tumor initiation." (PMID 36428690, 2022). "The roles of cadherins and PDPN in contact normalization described in this study should yield insight into fundamental mechanisms that affect the general process of cancer development and progression at the cellular level of the tumor microenvironment." (PMID 35177067, 2022). "Furthermore, PDPN-positive CAFs express high TGF-β and PDPN-positive CAF cases display high CD204 TAMs and low CD8/FOXP3 T cells, which are associated with an immunosuppressive tumor microenvironment." (PMID 35159384, 2022). "PDPN may be released into the circulationeither in soluble form or on the surface of tumor–derived microvesicles." (PMID 35814405, 2022). "However, an exception was the decreased expression of podoplanin on CAFs isolated from 4T1 tumor-bearing mice fed with 5000 IU of vitamin D3 and mice fed with a control 1000 IU diet and administered with calcitriol by gavage." (PMID 36230508, 2022). "The aim of this study is to evaluate a Ki-67 and podoplanin double immunostaining in HNSCC to observe the involvement of lymphatic vessels (LVs) in tumor and peritumoral areas, as well as the density of the tumor proliferation correlated with histopathological grading." (PMID 36077194, 2022). "PDPN-expressing CAFs promote tumor cell resistance to EGFR tyrosine kinase inhibitors." (PMID 35159384, 2022). "A total of 86% of cases showed increased podoplanin expression in the invasive front of the tumor." (PMID 36247509, 2022). "There is increasing evidence that podoplanin might contribute to tumor growth, invasion, and hematogenous spread." (PMID 36247509, 2022). "In tumor cells, PDPN enables migration and invasion by modulating the actin cytoskeleton." (PMID 36428690, 2022). "The combination of CLEC-2 and PDPN can induce platelet aggregation and strengthen tumor metastasis." (PMID 35659308, 2022). "Podoplanin enhances the extra organ extension of the tumor and promotes tumor progression." (PMID 36362726, 2022). "Interestingly, we found that PDPN mRNA levels were negatively correlated with tumor content and strongly correlated with inferred activated fibroblast levels." (PMID 34879110, 2021). "Interestingly, PDPN-overexpressing cancer cells evoke platelet aggregation, also known as tumor cell-induced platelet aggregation (TCIPA)." (PMID 34987523, 2021). "Although they found no changes in the rate of angiogenesis in knockouts compared with intact controls, expression of PDPN could be used as a tumor biomarker for unfavorable outcome." (PMID 34571991, 2021).
tumor (continued). "We hypothesize that in the TME, the high PDPN expression contributes to a highly contractile environment that acts as a barrier preventing T cell infiltration in the tumor bed." (PMID 34879110, 2021). "Therefore, inhibition of glycosylation or the expression of PDPN will serve as a potential strategy to prevent tumor cell progression." (PMID 34164422, 2021). "Collectively, our findings indicate that PDPN is crucial for maintaining key physiological properties and homeostasis of human CAFs leading to increased proliferation and differential signaling transduction, which ultimately supports tumor growth." (PMID 34879110, 2021). "Additionally, we performed FACS analysis on primary tumor samples to show on the protein level that CAFs also are a major source of PDPN within the tumor microenvironment." (PMID 34879110, 2021). "Flow cytometric analysis for CD26 (Dpp4) and CD34 expression confirmed that iCAFs represent a substantial fraction of the EYFP+ PDPN+ tumor fibroblasts and that the subsets of Ly6C+ CD34+ and Sca-1+ CD34+ fibroblasts were significantly expanded after artLCMV treatment." (PMID 34354077, 2021). "Additionally, CD8+ T-cells were in close contact with PDPN+ CAFs in the collagen-rich capsule of 4T1 tumours, and thus sequestered from the cancer cells in the centre of the tumour and unable to be effective." (PMID 34016130, 2021). "However, fundamental aspects of PDPN biology have remained largely uncharacterized, including its relevant binding partners and the function of PDPN in the tumor microenvironment." (PMID 34879110, 2021). "P-selectin on the platelet surface binds to the Sialyl-Lewisx-tetrasaccharide conjugate of PSGL-1 (P-selectin glycoprotein ligand-1) expressed on tumor cells, thus constituting a secondary level of platelet-tumor cell cohesion downstream of the Clec-2-podoplanin interaction." (PMID 33937274, 2021). "Studies from tumor cells suggested that PDPN may play a role in migration, involving rapid signaling events." (PMID 34879110, 2021). "Notably, it has been reported that PDPN expression is elevated at the leading edge of tumor tissues, which promotes cell surface extension and cell motility in keratinocytes." (PMID 34987523, 2021). "In addition, podoplanin can be highly expressed on tumor cells and the platelet CLEC-2/podoplanin axis was shown to promote tumor progression, metastasis, and cancer-induced thrombosis." (PMID 34235190, 2021). "PDPN molecules have platelet aggregation-stimulating domains and, are therefore, suggested to play a role in tumor-induced platelet activation, which in turn triggers epithelial-to-mesenchymal transition (EMT) and enhances the invasive and metastatic activities of tumor cells." (PMID 32581653, 2020). "Podoplanin expression is coordinately upregulated with both CD44v and CD44s isoforms in the skin upon a proinflammatory stimulus with TPA, and the expression of these proteins is coincidentally associated with a skin hyperplasia." (PMID 33003440, 2020). "For this analysis we focused on PDPN (FDR 6.43E-05, fold change 3.62) and LAMA4 (FDR 1.58E-09, fold change 3.77) because these molecules have been previously associated with cancer progression in other tumor types." (PMID 32571313, 2020). "Several studies also showed evidences of PDPN in regulating stem cells in normal and tumor tissues." (PMID 32408907, 2020). "According to the marker genes, these clusters were designated as blood endothelial cells (FLT1; clusters 0–3, 5, 6), lymphatic endothelial cells (PDPN: cluster 4), tumor endothelial cells (HSPG2: clusters 0 and 2–6), and normal endothelial cells (MT2A; clusters 0–6)." (PMID 33083004, 2020). "Intriguingly, it was reported that 237mAb, an antibody binds dominantly the Tn antigen of the glycopeptidic neoepitope found in the mouse tumour-associated glycoprotein podoplanin, does not recognise a conformational epitope." (PMID 34122956, 2020).
tumor (continued). "Furthermore, fibroblasts expressing high levels of podoplanin have been found to interact efficiently with endothelial cells, as well as affect the tumor vascular network by promoting pseudo-tube formation." (PMID 32604738, 2020). "However, an anti-tumor effect of anti-PDPN antibody therapy has so far been proven only in mouse models, and evaluation of the safety of PDPN-targeting therapies is required before first-in-human clinical trials." (PMID 33238582, 2020). "In addition to tumor cells, anti-PDPN staining was also evident in the cytoplasm of endothelial cells in tumor-adjacent blood vessels (arrowhead)." (PMID 32571313, 2020). "This suggests that calretinin and podoplanin have different functions in different cancer entities, which may either be tumor‐suppressive of tumor‐promoting function." (PMID 32533757, 2020). "In addition, as forced PDPN expression itself can alter the propensity of certain tumor cells in favor of EMT and enhance their invasive ability, it is also considered to be involved in the cell signaling system." (PMID 32581653, 2020). "Thus, targeting PDPN has the additional advantage of depleting CAFs which is essential for tumor progression." (PMID 32326079, 2020). "Moreover, EGFRover occurred more frequently in the tumours with a higher number of intratumoural lymphatic vessels and blood vessels assessed using podoplanin and CD34 staining, respectively (n = 472, Chi2 = 11.541, p = 0.009)." (PMID 32901137, 2020). "Additionally, we further characterized two ECM-associated factors, PDPN and LAMA4, and found that their expression was largely limited to tumor cells in HSA tissue." (PMID 32571313, 2020). "Through the data mining of a microarray dataset composed of matched tumor-normal tissues from forty OSCC patients, we distilled overexpressed genes statistically associated with angiolymphatic invasion, including DDR1, COL4A5, COL4A6 and PDPN." (PMID 32244515, 2020). "In addition to cell-intrinsic effects, PDPN is also believed to promote tumor metastasis by interacting with its receptor, CLEC2, on the platelets." (PMID 32571313, 2020). "Interestingly, binding of CD9 to podoplanin in tumor cells antagonizes podoplanin–CLEC–2 interaction, inhibiting platelet aggregation and metastasis." (PMID 33003440, 2020). "Podoplanin is also expressed on a wide variety of malignant tumors, which may contribute to tumor progression mainly by promoting aggregation and activation of platelet." (PMID 32260559, 2020). "This indicates that the relationship between CAFs and the tumour expression of PDPN could play a significant role in the progression of HNC." (PMID 31967978, 2020). "Furthermore, the anti-human PDPN antibody, NZ-12, showed an obvious anti-tumor effect against human malignant pleural mesothelioma in an orthotopic xenograft model by inducing ADCC activity." (PMID 33238582, 2020). "Therefore, in the current study, we compared the function of PDPN expressed in PTC derived cell lines with different genetic background on the modulation of cell motility, migration and invasion associated with tumor progression." (PMID 30654768, 2019). "Podoplanin, a mucin-type transmembrane glycoprotein, mediating cellular contractile properties and cytoskeletal reorganization, is upregulated at the leading edge of the tumor in metastatic and poorly differentiated cSCC." (PMID 31934531, 2019). "Expression of PDPN is upregulated in various tumor types, including squamous cell carcinoma, angiosarcoma, hemangioblastoma, malignant mesothelioma, and brain tumors, and correlates with increased tumor cell motility and metastasis." (PMID 31335913, 2019). "There is also evidence indicating a role for podoplanin in tumor angiogenesis." (PMID 30736372, 2019). "In this study, the association between the stage of the tumor and the expression of podoplanin was not significant (p=0.296)." (PMID 31508790, 2019). "Podoplanin is a membrane glycoprotein expressed on the surface of several tumor cells." (PMID 31337034, 2019).